KIT (KIT proto-oncogene, receptor tyrosine kinase)
Diseases named in the same sentence as KIT in open-access papers (continued):
Sharing a sentence is not in itself a finding about the gene and the disease.
thymic tumors (3 papers, 2013 to 2024). "Despite the best efforts to build preclinical and translational models to support the use of EGFR and KIT TKIs, these drugs ultimately showed limited activity across the spectrum of thymic tumors." (PMID 38254905, 2024). "Though several signaling pathways have been explored in thymic tumors, clinical trials with EGFR, KIT, VEGF, and IGF-1R, histone deacetylase, DNA methyltransferase, tropomyosin receptor kinase A, and, cyclin-dependent kinase inhibitors documented only modest clinical responses in advanced disease." (PMID 23765114, 2013).
undifferentiated carcinoma (3 papers, 2022 to 2024). A usually aggressive malignant epithelial neoplasm composed of atypical cells which do not display evidence of glandular, squamous, or transitional cell differentiation. "c-KIT expression was confirmed in lymphoepithelial carcinoma (LEP) but in a few cases of BCAC, oncocytic carcinoma, cystadenosarcoma, adenosquamous carcinoma, and undifferentiated carcinoma." (PMID 39858584, 2024).
vaginal melanoma (3 papers, 2015 to 2021). A primary malignant neoplasm of the vagina composed of malignant melanocytes. "The differences between our findings and published studies on KIT mutations in vulvar and vaginal melanomas could be due to the small numbers of samples in our series, different methodology or ethnic difference." (PMID 34102999, 2021).
Waardenburg syndrome (3 papers, 2011 to 2012). A disorder characterized by varying degrees of deafness and minor defects in structures arising from neural crest, including pigmentation anomalies of eyes, hair, and skin. "Although the Waardenburg syndrome genes PAX3, SOX10, MITF, EDN3 and EDNRB were not dramatically affected at the mRNA level, expression of the piebaldism gene KIT was significantly down-regulated upon loss of YY1." (PMID 22570637, 2012). "Thus, possible candidates for white coat colour (KIT on BTA6, KITLG on BTA5, PMEL on BTA5, TYR on BTA29) and other Waardenburg syndromes (WS) including PAX3 (WS1, WS3; on BTA2), EDNRB (WS4a; on BTA12), EDN3 (WS4b; on BTA13) and SOX10 (WS2e, WS4c; on BTA5) could be clearly excluded." (PMID 22174915, 2011).
acute basophilic leukemia (2 papers, 2010 to 2023). A rare acute myeloid leukemia in which the immature cells differentiate towards basophils. "Unlike in MCL, serum tryptase level is only slightly/moderately elevated, and no KIT mutations are found in MML and acute basophilic leukemia." (PMID 36980550, 2023).
acute erythroid leukemia (2 papers, 2016 to 2021). An acute myeloid leukemia characterized by a predominant immature erythroid population. "However, in 2005, Felli's group discovered that KIT, a well-known oncogene, is targeted by miR-221/222 in erythroblastic leukemia, thus illustrating miR-221/222's function as a tumor suppressor in human erythroblast cells." (PMID 27811362, 2016).
amyotrophic lateral sclerosis (2 papers, 2024 to 2025). Amyotrophic lateral sclerosis (ALS) is a neurodegenerative disease characterized by progressive muscular paralysis reflecting degeneration of motor neurons in the primary motor cortex, corticospinal tracts, brainstem and spinal cord. "Inflammation in peripheral motor axon degeneration in amyotrophic lateral sclerosis (ALS) is associated with mast cells’ activation and c-KIT inhibition abrogates TDP43 pathology in ALS." (PMID 40137158, 2025).
anaplastic astrocytoma (2 papers, 2013 to 2024).
Azoospermia (2 papers, 2023 to 2024). Absence of any measurable level of sperm,whereby spermatozoa cannot be observed even after centrifugation of the semen pellet. "AZFc_del may decrease the proliferation of c‐KIT‐positive spermatogonia, leading to severe oligozoospermia and even azoospermia." (PMID 38783578, 2024).
basal cell carcinoma (2 papers, 2019 to 2022). A carcinoma involving the basal cells. "Nuclear YAP-ir was observed in the KIT-positive region of five primary GIST samples as well as in basal cell carcinoma, used as positive control for nuclear YAP localization." (PMID 30956759, 2019).
bladder urothelial carcinoma (2 papers, 2014 to 2023). "Using immunohistochemistry, the present study demonstrated a high expression of CD117/KIT, HER2, and ERβ in the urinary bladder urothelial carcinoma." (PMID 37338655, 2023).
cancer of gallbladder (2 papers, 2017 to 2018). "Furthermore, another study has shown that FENDRR was co-expressed with KIT–an oncogene crucial in GIST development–in a gallbladder cancer." (PMID 30557328, 2018).
colorectal GIST (2 papers, 2024 to 2025). "Surprisingly, gastric GISTs comprised 11.0% of cases, there were no colorectal GISTs, and 5.1% of NF1-GISTs harbored a KIT or PDGFRA mutation." (PMID 40043354, 2025).
cystitis (2 papers, 2021 to 2023). Inflammation of the urinary bladder. "In 2017, expression level of PDGFR-β, VEGFR-2 and KIT were compared between canine MIUC tumors, cystitis samples and normal bladder tissue using IHC." (PMID 34680588, 2021).
fibroma (2 papers, 2022). A non-metastasizing neoplasm arising from the fibrous tissue. "In this setting, some benign ovarian tumors such as fibroma/fibrothecoma also enter the differential diagnosis; SF-1 and inhibin, in addition to c-KIT and DOG-1, can be used to differentiate these lesions." (PMID 35885469, 2022).
Hand-foot syndrome (2 papers, 2025). "Moreover, regorafenib’s inhibition of multiple kinases (e.g., RAF, KIT) may lead to greater off-target toxicity, such as hand-foot syndrome." (PMID 40994649, 2025).
helminth infection (2 papers, 2020 to 2026). "Although epithelial KIT is dispensable for homeostatic turnover, KIT deletion from tuft cells during helminth infection reduces tuft cell hyperplasia and delays helminth clearance." (PMID 41739917, 2026).
histiocytic sarcoma (2 papers, 2023). An aggressive malignant neoplasm with a poor response to therapy, usually presenting as stage III/IV disease. "One study investigated PDGFR-β and KIT expression by IHC in 15 cases of various feline histiocytic disorders (five feline progressive histiocytoses, eight histiocytic sarcomas and two hemophagocytic histiocytic sarcomas)." (PMID 37835664, 2023).
Hypercholesterolemia (2 papers, 2020 to 2021). An increased concentration of cholesterol in the blood. "In addition to c-KIT inhibitors, interestingly Fluvastatin, a statin drug used in the treatment of hypercholesterolemia not only suppresses IgE signaling in MCs but also induces apoptosis by inhibiting stem cell factor (SCF) induced survival signals in primary and in c-KIT mutated MCs." (PMID 34631562, 2021).
Hypoglycemia (2 papers, 2007 to 2024). A decreased concentration of glucose in the blood. "The association of this KIT mutation with non-islet cell tumor induced hypoglycemia has yet to be established." (PMID 17229322, 2007).
inflammatory bowel disease (2 papers, 2014 to 2024). A spectrum of small and large bowel inflammatory diseases of unknown etiology. "The phenomenon of a dramatic decrease in KIT immunoreactivity coupled to an increase in total mast cell numbers was already shown in IC and inflammatory bowel disease patients, and was explained by internalization of KIT upon binding of its ligand SCF." (PMID 24760514, 2014).
intracranial germinomas (2 papers, 2007 to 2020). "In pediatric intracranial germinomas, KIT-mutated cases were linked to worse prognosis." (PMID 32999426, 2020).
Lynch syndrome (2 papers, 2012 to 2019). An autosomal dominant hereditary neoplastic syndrome characterized by the development of colorectal carcinoma and a high risk of developing endometrial carcinoma, gastric carcinoma, ovarian carcinoma, renal pelvis carcinoma, and small intestinal carcinoma. "Unlike other cancer predisposition syndromes such as Lynch Syndrome, some of the germline mutations that result in inherited GIST, such as mutations involving KIT and PDGFR genes, produce abnormal proteins that can be inhibited by currently available targeted therapy." (PMID 23036227, 2012).
medullary thyroid cancer (2 papers, 2011 to 2019). "Cabozantinib (XL184), targeting VEGFR1/2, MET, RET, KIT and FLT3, has been assessed in several cell line models and has been approved by the FDA for the treatment of progressive medullary thyroid cancer." (PMID 31040922, 2019).
multiple sclerosis (2 papers, 2018 to 2025). A progressive autoimmune disorder affecting the central nervous system resulting in demyelination. "Masitinib, a c-KIT inhibitor, is currently in phase 3 clinical trials for AD and multiple sclerosis." (PMID 40137158, 2025). "Mastinib is an example of a c-KIT inhibitor that is being investigated as a potential therapy in AD and multiple sclerosis." (PMID 40137158, 2025).
osteosclerosis (2 papers, 2020 to 2026). Abnormally high bone density. "AdvSM patients with increased BMD/osteosclerosis had a more aggressive phenotype, e.g., a higher mast cell burden in the bone marrow compared to our ISM patients, and the same was found to hold true for serum tryptase, KIT D816V EAB and alkaline phosphatase." (PMID 31980928, 2020).
ovarian failure (2 papers, 2024). "Variations in KIT/KIT-ligand cause ovarian insufficiency in rodents, but their role has yet to be elucidated in women affected by POI." (PMID 39391877, 2024).
overactive bladder (2 papers, 2011 to 2024). Symptom of overactive detrusor muscle of the urinary bladder that contracts with abnormally high frequency and urgency. "The population of KIT or vimentin immunoreactive ICCs was increased in subserosal layers and their distribution was altered in the suburothelial layer in PBOO bladders, suggesting that the altered distribution of ICCs may contribute to the pathophysiology of bladder overactivity." (PMID 21785586, 2011).
pilocytic astrocytoma (2 papers, 2010 to 2013). Pilocytic astrocytoma is a rare subtype of low-grade glioma of the central nervous system characterized by a well circumscribed, often cystic, brain tumor with a discrete mural nodule and long, hair-like projections that extend from the neoplastic astrocytes. "A strong association was found between age at diagnosis and KIT expression in the endothelial cells of pilocytic astrocytomas." (PMID 20030644, 2010). "In pilocytic astrocytomas, endothelial cell KIT expression is associated with a young age at the time of the diagnosis, and with tumor cell expression of KIT, phosphorylated KIT, and VEGFR‐2." (PMID 20030644, 2010). "They found that 35% of pilocytic astrocytomas express KIT, as do some of the normal brain specimens." (PMID 23717811, 2013). "We detected moderate or strongly KIT and phospho‐KIT expression in endothelia of 37% and 35% of pilocytic astrocytomas using immunohistochemistry, and confirmed presence of KIT mRNA in tumor microvessel endothelial cells using in situ hybridization." (PMID 20030644, 2010). "KIT and phospho‐KIT were moderately or strongly expressed in tumor endothelia of 37% and 35% of pilocytic astrocytomas, respectively, whereas marked SCF and VEGFR‐2 expression was uncommon." (PMID 20030644, 2010). "Pilocytic astrocytomas that expressed KIT in tumor cells expressed frequently KIT, phospho‐KIT and SCF in the tumor microvessel endothelial cells as well, but not endothelial cell VEGFR‐2." (PMID 20030644, 2010). "Taken together, these findings suggest that endothelial cell KIT may have a role in angiogenesis of pilocytic astrocytomas and some other types of juvenile brain tumors." (PMID 20030644, 2010). "The SCF and KIT‐mediated signaling may be important in tumor angiogenesis of pilocytic astrocytomas and some other types of juvenile brain tumors." (PMID 20030644, 2010). "KIT gene copy number was assessed using CISH in 9 pilocytic astrocytomas." (PMID 20030644, 2010). "Pilocytic astrocytomas that expressed VEGFR‐2 expressed often endothelial cell KIT (P = 0.022) and phospho‐KIT (P = 0.049), and tended to express SCF in the tumor endothelial cells (P = 0.077)." (PMID 20030644, 2010). "Associations between tumor cell and tumor endothelial cell expression of KIT, phosphorylated KIT, SCF and VEGFR‐2 in juvenile pilocytic astrocytomas." (PMID 20030644, 2010). "Moderate (++) or strong (+++) KIT expression was detected in tumor endothelial cells in 13 (37%) out of the 35 juvenile pilocytic astrocytomas, whereas in none of the cases the tumor cells expressed KIT at these levels." (PMID 20030644, 2010). "Expression of KIT, phosphorylated KIT, SCF, and VEGFR‐2 in juvenile pilocytic astrocytomas." (PMID 20030644, 2010). "Expression of KIT in pilocytic astrocytoma may be more frequent than this, as we did not carry out serial sectioning of the tumors in order to preserve tissue for possible future diagnostic needs." (PMID 20030644, 2010). "Pilocytic astrocytomas do not usually show overt tissue necrosis, and the majority of the tumors did not express HIF‐1α suggesting that tumor endothelial cell KIT expression may not have been HIF‐1α and hypoxia‐mediated." (PMID 20030644, 2010).
rectal adenocarcinoma (2 papers, 2014 to 2020). "This is the case for rectum adenocarcinoma: its five oncogenes are BCL2, KIT, KLF4, MET, and PDGFRA." (PMID 31900418, 2020).
rectal tumors (2 papers, 2020 to 2024). "The rectal tumors in this study harbored KIT exon 11 mutations, while both analyzed colonic cases were wild-type for KIT/PDGFRA/RAS." (PMID 39199677, 2024). "In the low‐risk GIST group, patients with rectal tumors or KIT exon 11 deletions involving two or more codons had relatively high recurrence rates." (PMID 32697050, 2020).
renal fibrosis (2 papers, 2021 to 2022). A final common manifestation of a wide variety of chronic kidney diseases characterized by glomerulosclerosis and tubulointerstitial fibrosis. "Pathological staining showed that the lumen of renal tubules exhibited significantly reduced apoptosis, morphological damage was alleviated and the renal fibrosis area was markedly reduced in the KIT-bFGF group." (PMID 35615568, 2022). "Treatment with KIT-bFGF in rat models with renal I/R injury could attenuate renal tubule damage, renal fibrosis, cell apoptosis and effectively improved functional recovery at different stages." (PMID 35615568, 2022). "Treatment with KIT-bFGF (21.80 ± 2.47%, 16.36 ± 7.72%) significantly attenuated renal fibrosis (blue staining), and the fibrotic area was significantly smaller than that in the bFGF-treated (30.62 ± 4.03%, 36.59 ± 5.20%) and PBS-treated (50.76 ± 5.77%, 44.51 ± 8.11%) groups." (PMID 35615568, 2022). "Thus, KIT-bFGF played an important role in decreasing renal fibrosis after renal I/R injury." (PMID 35615568, 2022).
skin reaction (2 papers, 2010 to 2020). "Other investigators have proposed that certain skin reactions may result from an inhibition of KIT, found in basal cells." (PMID 20718969, 2010).
steatosis (2 papers, 2007 to 2024). Increased lipid within the cytoplasm of cells. "Thus, the steatosis could be an indirect consequence of a defect in the differentiation or the proliferation of hepatic progenitor cells leading to the loss of KIT+ cells observed in Sco5/lac or Sow3/lac animals." (PMID 17612398, 2007). "Decreasing the activity of KIT to a certain steatosis threshold will modify the pool of stem cells that will affect either the development of the liver and the post-natal hepatic homeostasis." (PMID 17612398, 2007). "This is a first report involving KIT in the control of lipid metabolism in neonates and opening new perspectives for understanding juvenile steatosis." (PMID 17612398, 2007). "Now, KIT should be considered as one of the endogenous factors that could lead to steatosis." (PMID 17612398, 2007).
testicular dysgenesis syndrome (2 papers, 2025 to 2026). A syndrome comprising testicular germ cell cancer, cryptorchidism and some cases of hypospadias and male infertility with impaired development of the testis. "Research is ongoing on the role of microenvironmental factors, chromosomal instability, testicular dysgenesis syndrome, epigenetic machinery, KIT/RAS alterations, and elevated KIT mRNA expression." (PMID 41523526, 2025).
thrombocythemia (2 papers, 2021 to 2025). "In summary, GIST with secondary thrombocythemia is a rare clinical case, and it is even rarer to have a mutation in the c-KIT (Exon13) gene that exhibits significant platelet elevation." (PMID 40837560, 2025). "Future clinicopathologic series or registry-based investigations are needed to determine whether thrombocytosis represents a consistent phenotype among GIST patients with KIT Exon 13 mutations or remains an incidental finding in rare cases." (PMID 40837560, 2025). "This case was diagnosed as c-KIT Exon 13 mutant GIST with significant thrombocytosis." (PMID 40837560, 2025).
ulcer (2 papers, 2021 to 2025). "Notably, we observed increased fibroblast-to-immune signaling through the midkine (MK), hepatocyte growth factor (HGF), IGF-binding protein (IGFBP), and KIT (stem cell factor) pathways in GK-high ulcers." (PMID 41583446, 2025).
undifferentiated pleomorphic sarcoma (2 papers, 2018 to 2021). An undifferentiated soft tissue sarcoma characterized by the presence of a pleomorphic malignant cellular infiltrate. "We present genomic analysis of a radiation-induced intracranial undifferentiated pleomorphic sarcoma in an 83-year-old woman with notable KIT and PDGFRA alterations." (PMID 33747576, 2021).
varicocele (2 papers, 2017 to 2022). A condition characterized by the dilated tortuous veins of the spermatic cord with a marked left-sided predominance. "However, the effectsof cytokines and KIT signaling in the inflammatoryprocess of varicocele are predicatable." (PMID 28868836, 2017).